HIF1A (hypoxia inducible factor 1 subunit alpha)
Diseases named in the same sentence as HIF1A in open-access papers (continued):
Sharing a sentence is not in itself a finding about the gene and the disease.
leukemia (continued). "Taken together, our data indicate that hampering HIF-1α functions affects different aspects of APL biology that include cell migration and self-renewal, thus resulting in delayed leukemia progression." (PMID 24711541, 2014). "Strong inhibition of HIF-1α by EZN-2968 recapitulated more efficiently what was previously observed by chronic HIF-1α silencing: blockade of cell migration and CFU-L efficacy upon re-plating, as well as delayed leukemia progression." (PMID 24711541, 2014). "As a consequence, inhibiting HIF-1α in APL mouse models delays leukemia progression and exquisitely synergizes with ATRA to eliminate leukemia-initiating cells (LICs)." (PMID 24711541, 2014). "Moreover, HIF-1α inhibition also synergized with ATRA in promoting leukemia de-bulking, therefore suggesting that a strong inhibition of HIF-1α may cooperate with ATRA not only to blunt the leukemia-initiating capacity of APL cells, but also their in vivo survival and/or differentiation." (PMID 24711541, 2014). "Methylcellulose re-plating assays showed that NB4 CFU-L (colony-forming unit leukemia) increased upon serial re-plating only in cells expressing HIF-1α, thus indicating that self-renewal of CFU-L requires HIF-1α." (PMID 24711541, 2014). "The overactivity of glycolytic pathways, particularly through the stabilization of hypoxia-inducible factor 1-alpha (HIF-1α) under normoxic conditions, promotes survival signals and inhibits cell death pathways, thereby contributing to leukemia progression and chemotherapy resistance." (PMID 40282531, 2025). "Urged expression of RUNX1 inhibits HIF-1α transcriptional activity and decreased target gene expression, such as VEGF, but that of HIF-1α enhances RUNX1 transcriptional activity, confirming the role of HIF-1α and RUNX1 in angiogenesis and differentiation of leukemia cells." (PMID 36231060, 2022). "A drug screen using the same model revealed that echinomycin, an inhibitor of HIF1A, could antagonize the KRASG12V-induced leukemia phenotype." (PMID 34580712, 2022). "Studies have shown that the presence of leukemia stem cells (LSC) under an extremely hypoxic microenvironment is called “bone niche,” and HIF-1α expression might be increased." (PMID 35528614, 2022). "Perhaps the most concordant role of HIF1α across diverse types of leukemia is to promote maintenance of leukemia stem cells (LSCs), a function that HIF1α also exerts in the non-malignant hematopoietic stem cell compartment." (PMID 36059690, 2022). "Various types of leukemia have an abnormally high expression of the HIF-1α gene, so the study of HIF-1α inhibitors may become a new strategy for the treatment of leukemia." (PMID 35684364, 2022). "As stated at the beginning of this chapter, studies on the role of HIF1α and HIF2α in leukemia failed to produce universal consent, especially in AML and CLL where contrasting evidence has been reported." (PMID 36059690, 2022). "Conversely, leukemia and lymphoma cells markedly depend on the activation of HIF-1a signaling during exposure to biguanides, being resistant to biguanide-induced complex I dysfunction mediated by HIF1α-regulated transcriptional rewiring of glucose metabolism." (PMID 35804992, 2022). "In addition, we recently published that leukemia cell RS4;11 co-expressed both with HIF-1α and YY1 under hypoxia, which correlated with a downregulation of Fas expression." (PMID 35163649, 2022). "In order to demonstrate whether the inhibition of HIF-1α can modify YY1 expression, we incubated the leukemia cell line RS4;11 in normoxia and hypoxia conditions for different times." (PMID 35163649, 2022). "The impairment of HIF-1α and AHR provided promising results against leukemia and myeloma." (PMID 34572746, 2021). "In addition, unresponsive MLL-rearranged leukemia cells expressed increased levels of MEIS1, an important leukemogenic MLL target gene that plays a role in regulating metabolic phenotype through HIF1α." (PMID 30670779, 2019).
leukemia (continued). "To deliver HIF1A siRNA into MLL-r leukemia cells we used a nonviral lipid nanoparticle developed by our group to self-assemble and deliver siRNA to tumor cells." (PMID 30670779, 2019). "In three different murine AML models, the absence of HIF1α did not inhibit (and in certain models in fact promoted) leukemia development, hence challenging the assumption that HIF1α is a therapeutic target in AML." (PMID 30781787, 2019). "Models used to characterize HIF1A and HIF2A as tumor suppressor genes in leukemias." (PMID 26955619, 2016). "Models used to characterize HIF1A and HIF2A as oncogenes in leukemias." (PMID 26955619, 2016). "Taken together, these studies present an intricate scenario where the role of HIF-1α in AML is still controversial and it may change at different stages of leukemia development and/or in specific leukemia contexts." (PMID 27447550, 2016). "Taken together these data indicate that acute silencing of HIF-1α impairs important pro-leukemogenic functions like basal cell migration and chemotaxis of AML-M5 cells in vitro and may therefore result in impaired leukemia progression or propagation in vivo." (PMID 27447550, 2016). "Ex vivo APL blasts electroporation with EZN-2968 led to significant impairment in the expression of HIF-1α and HIF-target genes and inhibited basal and SDF-1-directed cell migration, CFU-L formation and leukemia involvement in peripheral blood, leading to increased mice survival." (PMID 24711541, 2014). "Although not thoroughly investigated in our studies, it is also likely that leukemia propagation is associated with derangements and non-functionality of vascular architecture which might contribute to progressive hypoxia despite stimulation of angiogenesis through HIF-1α." (PMID 21853076, 2011). "Notably, HIF-1α exerts protective effects against cGVHD while preserving graft-versus-leukemia (GVL) activity, offering a unique therapeutic advantage for balancing cGVHD suppression and leukemia relapse prevention." (PMID 40791591, 2025). "Of note, the majority of the studies that we will describe have focused on defining the functions of HIF1α, whereas HIF2α has been much less investigated and detailed analyses on the functions of this factor in leukemia establishment and progression are still lacking." (PMID 36059690, 2022). "Interestingly, a similar role of stimulating leukemia dissemination was reported in AML sub-types including acute promyelocytic and monocytic leukemia, where HIF1α induces chemokine-dependent cell migration and transcriptional programs of epithelial to mesenchymal transition." (PMID 36059690, 2022). "Expression of HIF-1α and HIF-2α, which are regulated by calcium dependent pathways and involved in modulation of mitochondrial proteins including members of the ETC, were decreased in TRPM2-depleted U937 leukemia cells, as was the downstream transcription factor FOXO3a." (PMID 32312983, 2020). "MLL-r leukemia cells sensitive to CCI-006 thus present with a different metabolic profile compared to unresponsive MLL-r leukemia cells, exemplified by lower expression levels of HIF1α, a greater resistance to glycolysis inhibitors and a differentially composed mitochondrial respiratory chain." (PMID 30670779, 2019). "However, our findings in A20 cells did not exclude the possibility that in certain leukemia cells HIF-1α inhibition remains an effective anti-leukemia regimen." (PMID 28183349, 2017). "Therefore, our data indicate that HIF-1α exerts context-specific oncogenic functions in AML, with a pro-invasive role in AML-M5 that may be targeted to reduce leukemia dissemination." (PMID 27447550, 2016). "Furthermore, several studies have reported elevated levels of HIF-1α in AML, where it mediates the capacity of leukemic cells to migrate and invade extramedullary sites, suggesting that hypoxia and HIF-mediated signaling may play a crucial role in leukemia." (PMID 35938170, 2022).
leukemia (continued). "Of note, the deletion of β-catenin or HIF-1α did not impair the growth or viability of bulk tumor cells, suggesting that components of the Wnt pathway and HIF specifically support leukemia stem cells." (PMID 34026651, 2021). "Neither Hif1α nor PD-L1 depletion inhibited the in vitro growth and in vivo development of MLL-AF9 leukemia, indicating that both genes are dispensable for leukemia progression in mice with no treatment." (PMID 31653912, 2019). "By using murine models of aGVHD and GVL, we show here that HIF-1α inhibition by echinomycin treatment significantly reduces aGVHD without weakening GVL, resulting in prolonged leukemia free survival." (PMID 28183349, 2017). "In leukaemia settings, by adjusting EZN-2208 dosage to non-cytotoxic concentrations, we have demonstrated that this compound can impair myeloid leukaemia and CLL progression in vivo via HIF-1α inhibition." (PMID 32397871, 2020). "Upregulation of hypoxia-regulated factors occurred rapidly in MSCs when cocultured with AML, but this is not maintained after leukemia cells are withdrawn from the culture, potentially explaining why STC1 and HIF-1α have not been identified in AML patient–derived MSCs." (PMID 32364536, 2020). "For instance, deletion of the HIF1α gene in mouse hematopoietic stem and progenitor cells alongside retroviral transfer of AML oncogenic drivers (MLL-AF9, AML1-ETO, or MEIS1 and HOXA9) failed to impact leukemia initiation, progression and LSCs self-renewal by serial transplantation experiments." (PMID 36059690, 2022).
rheumatoid arthritis (81 papers, 2009 to 2026). A chronic, systemic autoimmune disorder characterized by inflammation in the synovial membranes and articular surfaces. "HIF-1α was also implicated in inflammatory conditions, including rheumatoid arthritis, where upregulations of HIF-1α and iNOS were both seen in synovial fluids." (PMID 40508229, 2025). "Under inflammatory conditions in rheumatoid arthritis (RA), several molecules such as IL-1β, IL-6, TNF-α, IL-17, and hypoxia-inducible factor-1α (HIF-1α) are produced, which can mediate bone loss." (PMID 40153574, 2025). "HIF‐1α can directly regulate the levels of all three cytokines in rheumatoid arthritis synovial fibroblasts." (PMID 39295108, 2024). "For example, in the context of rheumatoid arthritis, HIF-1α was shown to directly interfere with the production of TNF-α, IL-1β, IL-6 and IL-8." (PMID 38273861, 2023). "These are consistent with a previous study where HMGB1 induced the expression of HIF-1α and angiogenesis in rheumatoid arthritis." (PMID 35586052, 2022). "The increase in bone resorption in rheumatoid arthritis is driven by the hypoxia-inducible transcription factor HIF-1α." (PMID 35801079, 2022). "Many studies have also found that HIF-1α plays a certain role in the pathogenesis of rheumatoid arthritis (RA)." (PMID 35684364, 2022). "Therefore, the upregulation of synovium-derived HIF-1α occurs in the pathogenesis of rheumatoid arthritis (RA) and osteoarthritis (OA), which are hypoxia-associated diseases." (PMID 34007291, 2021). "In the synovium of rheumatoid arthritis, the content of HIF-1α is increased, which is crucial for IL-1β." (PMID 33995016, 2021). "It has been shown that extracellular HMGB1 induces angiogenesis and promotes rheumatoid arthritis via NF-κB/HIF-1α activation, and cilostazol inhibits NF-κB-mediated transcription leading to the inhibition of synovial angiogenesis." (PMID 32328193, 2020). "In this study, we demonstrated that the expression of HIF-1α was significantly up-regulated in rheumatoid arthritis tissue which indicated that the hypoxia condition in the microenvironment." (PMID 28053286, 2017). "In our study, we also demonstrated that the expression of HIF-1α, which is a marker of hypoxic stress, is significantly increased in the animal with rheumatoid arthritis." (PMID 28053286, 2017). "Firstly, we found the high expression of HIF-1α by IHC in the animal with rheumatoid arthritis which indicated the incidence of rheumatoid arthritis is associated with hypoxia microenvironment." (PMID 28053286, 2017). "Since all SF exhibited a similar response to HIF-1α silencing, we used SF from rheumatoid arthritis (RA) patients." (PMID 28623342, 2017). "A previous study also revealed that HIF-1α expression is strongly correlated with inflammation and angiogenesis in rheumatoid arthritis." (PMID 23991178, 2013). "Activated macrophages in inflamed joints of patients suffering from rheumatoid arthritis express HIF-1α." (PMID 23483870, 2013). "In this study we showed that HIF-1α is expressed in synovial tissue from rheumatoid arthritis patients, and also in macrophages isolated from RA SF." (PMID 20353560, 2010). "They demonstrated up-regulation of VEGF/VEGFR, HIF-1α, and inhibitor of differentiation-2 in blood vessels from inflamed regions of patients with rheumatoid arthritis." (PMID 19292924, 2009). "In addition, inhibition of the ERK/HIF-1α/GLUT-1 pathway has been shown to downregulate macrophage glycolysis in a rat rheumatoid arthritis model." (PMID 41203617, 2025). "Additionally, CRT demonstrated potential in treating rheumatoid arthritis by regulating the PI3K/HIF1α/NOS2 signaling pathway." (PMID 39130629, 2024). "The results showed that AMSP-30m treatment induced anti-arthritic effects through its anti-angiogenic and anti-inflammatory activity, suggesting that HIF-1α regulation may serve as a treatment for rheumatoid arthritis." (PMID 38247510, 2024).
rheumatoid arthritis (continued). "Besides, in rheumatoid arthritis, poor oxygen supply to immune cells infiltrating the synovial membrane upregulates HIF-1α expression and induces ROS overproduction." (PMID 37507801, 2023). "In addition to several cancer pathologies, succinate-induced HIF1A stabilization has been demonstrated to play a role in inflammation and rheumatoid arthritis." (PMID 30809153, 2019). "As a transcription factor, HIF-1α regulates the expression of genes encoding proteins involved in angiogenic growth factors, such as vascular endothelial growth factor (VEGF) and TGF-β, in rheumatoid arthritis." (PMID 30755787, 2019). "There is evidence that points out the key role of HIF-1α in the regulation of several pathophysiological processes such as rheumatoid arthritis (RA) and systemic lupus erythematous, especially producing synovial inflammation as well as glomerular and interstitial inflammation." (PMID 28484714, 2017). "In the tissues of rheumatoid arthritis, we could observe that the expression of HIF-1α was significantly up-regulated, which indicated that the hypoxia condition in the microenvironment." (PMID 28053286, 2017). "Hypoxia-inducible factor-2α (HIF-2α) is sufficient to cause experimental rheumatoid arthritis and acts to regulate the functions of fibroblast-like cells from tissue surrounding joints, independent of HIF-1α." (PMID 24914685, 2014). "We have also previously successfully regulated HIF-1α expression in synovial cells and rheumatoid arthritis (RA) animal models using a hypoxic environment." (PMID 40168275, 2025). "In this study, we investigated the inhibitory effects of emodin on pyroptosis in rheumatoid arthritis (RA) synovial cells by modulating the HIF-1α/NLRP3 inflammasome pathway and mitochondrial autophagy." (PMID 40728955, 2025). "Additionally, in some autoimmune diseases such as rheumatoid arthritis, diabetes mellitus type 1, multiple sclerosis and intestinal inflammatory disease, among others, high concentrations of HIF-1α have been reported, which correlates with a higher activity of the disease." (PMID 40963621, 2025). "High levels of hypoxia and HIF‐1α are associated with many of these conditions, including asthma, COPD, rheumatoid arthritis (RA), colitis and atherosclerosis." (PMID 32633061, 2020). "Hypoxia promotes HIF-1α expression in rheumatoid arthritis (RA), which is reported to induce macrophages M1 subtype polarization by increasing ROS production." (PMID 33298860, 2020). "Similarly, in rheumatoid arthritis, HIF-1a perpetuates the development of RA by activating pathways involved in synovial inflammation, angiogenesis, cartilage destruction, and bone erosion." (PMID 38311719, 2024). "WTD attenuates rheumatoid arthritis by inhibiting angiogenesis and regulating the PI3K/AKT/mTOR/HIF-1α pathway." (PMID 37221510, 2023). "HIF-α has three isoforms (HIF-1α, HIF-2α, HIF-3α), and it has been reported that HIF-2α is mainly expressed in FLSs in the joint cavity of patients with rheumatoid arthritis." (PMID 35366946, 2022). "To date, HIF-1α is recognized to be overexpressed in several inflammatory autoimmune diseases, such as systemic lupus erythematosus (SLE), rheumatoid arthritis, and function of HIF-1α is dysregulated in these diseases." (PMID 36761171, 2022). "The hypoxia inducible factor-1α (HIF-1α) and vascular endothelial growth factor (VEGF) play a key role in synovial angiogenesis in rheumatoid arthritis (RA)." (PMID 31316573, 2019). "Knocking down HIF-1α compromised IL-33 expression in rheumatoid arthritis synovial fibroblasts (RASF), while enforcing HIF-1α expression in RASF substantially upregulated IL-33 levels." (PMID 23967327, 2013).